TNF (tumor necrosis factor)
Diseases named in the same sentence as TNF in open-access papers (continued):
Sharing a sentence is not in itself a finding about the gene and the disease.
infection (continued). "Regardless of the reason for the lower risk for infection with time, some risk is always present, so physicians should remain vigilant during the course of treatment with infliximab or any other anti-TNF-α therapy." (PMID 20569501, 2010). "This could in turn force the host to reprogram its own response to the infection, by silencing pro-inflammatory immune signaling pathways dependent on chemokines, IFNγ and TNF." (PMID 20824205, 2010). "Of interest in a similar study it has been shown that infection of human alveolar macrophages with virulent M. tuberculosis strains in vitro induced the secretion of significantly higher levels of bioactive TNF than attenuated strains correlating with their ability to multiply intracellularly." (PMID 20652022, 2010). "This study confirms this data specifically for TJA infections in patients exposed to TNFα blockers." (PMID 20637100, 2010). "We first determined if infection with MtbΔnuoG resulted in an increase of secreted TNF-α." (PMID 20421951, 2010). "Amplification of immune responses to infection in the kidney may also occur, as the proinflammatory cytokines TNF-α and IFN-γ have been shown to induce renal expression of Tlr2 and Tlr4." (PMID 19845042, 2009). "Similar to German Landrace pigs, the TNF-α production by blood leukocytes from the Large White pigs increased significantly from pre- to post-infection, whereas the expression of this marker remained constant independent of the infection time when Pietrain and Hampshire cells were used." (PMID 19383119, 2009). "In LMMs with untransformed TLR variables as the response, the predicted reductions in TNF-α production in mice in the highest louse infection category in relation to mice uninfected with lice were 49% for TLR2/HKLM, 55% for TLR2/zymosan, 59% for TLR9 and 56% for TIR." (PMID 19386086, 2009). "At 8 h post-infection, TNF and IFN-β induction was measured by RT-PCR." (PMID 19922606, 2009). "However, mice supplemented with L. casei showed lower levels of TNF-α and IL-1β than the control group on d 5 post-infection." (PMID 19835595, 2009). "TNF-α gene expression responses to ΔPT infection remained near background levels throughout." (PMID 19759900, 2009). "In addition to eliciting neutrophil migration to the site of infection, mast cell-derived TNF evokes dendritic cell trafficking to draining lymph nodes." (PMID 23283207, 2009). "In comparison, TNF-α−/−, MyD88−/−, IL-12−/− or IFN-γ−/− C57BL/6 mice, normally thought of as highly susceptible mice, display necrotic lesions only after 4 or 6 weeks of infection and mutilation is observed only after 8–10 weeks." (PMID 19557162, 2009). "The tumour necrosis factor-alpha (TNF-α) was detectable in milk at 9 h post-infection." (PMID 19765294, 2009). "The early increase of TNF-α is required to an adequate antibacterial response at an infection site." (PMID 19835595, 2009). "Similarly, we observed a significant reduction of IFN-γ and TNF-α production following infection of MyD88KO compared to WT NOD mice." (PMID 19122812, 2009). "TNF-α production did not vary among infection groups, but Pcc infection was associated with significantly elevated IFN-γ production compared to uninfected and Nb-infected mice (P for Pcc main effect <0.0001)." (PMID 19951425, 2009). "Infection of human lung epithelial cells with Mycoplasma pneumoniae resulted in increased expression of proinflammatory cytokines interleukin IL-8, tumour necrosis factor alpha (TNFα) and IL-1β mRNA." (PMID 19806192, 2009). "Because most physicians would be reluctant to prescribe anti–TNF-α therapy to patients with known or obvious active infections, we suspect that most extrapulmonary infections (primarily soft tissue infections) in our series likely developed in patients after they began anti–TNF-α therapy." (PMID 19861045, 2009). "The defects observed in LPS- and infection-induced TNF-α production in cIAP-1 KO macrophages could be restricted to LPS-induced pathways." (PMID 19657383, 2009).
infection (continued). "Four of these genes also showed >1.5 fold up-regulation in H5N1- compared with H1N1-infected cells at 3 h post-infection: TNF, IFN-induced protein with tetratricopeptide repeats 2 (IFIT2), macrophage inflammatory protein 1-β (CCL4L1), and phorbol-12-myristate-13-acetate-induced protein 1 (PMAIP1)." (PMID 20011590, 2009). "In vitro stimulation of bronchoalveolar lavage fluid (BALF) and blood leukocytes with A. pleuropneumoniae, Streptococcus suis, PMA and LPS led to production of different amounts of H2O2, NO and TNF-α, depending on the stimulus, individual, breed and time of infection." (PMID 19383119, 2009). "Most likely, this apparent paradox may reflect that the samples were taken from animals that had reached a late stage of disease, a stage where the initial rise in TNF levels during the early phase of infection may have declined." (PMID 19956711, 2009). "Patients should be instructed regarding the rudiments of differentiating simple viral illnesses and minor infections from those with the potential to cause serious harm, and should be instructed to inform their TNF-α inhibitor prescriber when signs of the more serious infections occur." (PMID 20101303, 2009). "High levels of TNFα are found in adipose tissue fromHIV-1-infected patients even before treatment and are part of a proinflammatoryenvironment already present in adipose tissue as a consequence of long-termHIV-1 infection." (PMID 19081837, 2009). "In contrast to TNF−/− mice, TNFtm/tm mice were able to control infection at 8 weeks." (PMID 18544042, 2008). "In mammals, LPS-triggered TNF release at a site of injury/infection is critical to mobilize the immune and inflammatory processes required to fight the infection, but in the rare cases when this reaction becomes uncontrolled and systemic, the shock will rapidly kill the host." (PMID 18654628, 2008). "At day 4 post-infection, TNF-α secretion was indeed twofold higher in macrophages (of which 70% had differentiated into FMs) infected with M.tb than in those infected with M. smegmatis, as measured both by ELISA and RNA quantification (Peyron, unpublished observations)." (PMID 19002241, 2008). "Our data in this infection model using the Δ1-12 TNF mutant mouse shows a reduced protective immune response during mycobacterial infection when compared to previous findings in which a membrane TNF transgenic mutant or the Δ1-9,K11E mutant were used." (PMID 18544042, 2008). "Both the presence of IL-6 and TNF-α after inoculation in the two animals that remained clinically healthy could indicate a subclinical infection with B. hyodysenteriae." (PMID 18700003, 2008). "While TNF−/− mice displayed an uncontrolled infection with significantly increased CFU already at 4 weeks (P < 0·05), the TNFtm/tm mice showed at least a partial control of mycobacterial growth, with CFU values significantly less (P < 0·05) than TNF−/− mice at 45 days." (PMID 18544042, 2008). "It has to be noted, however, that the differences in bacterial numbers between TNF-α deficient mice and their controls were not seen until day 10 after infection." (PMID 18498620, 2008). "Therefore, the sole expression of membrane TNF provided partial protection against H37Rv infection and the data using the double transgenic mice indicate that membrane TNF signalling through TNF-R2 confers the protective effect of membrane-bound TNF." (PMID 18544042, 2008). "The partial protection that is generated in TNFtm/tm mice could indicate local cell-to-cell TNF signalling by membrane expressed TNF on T cells or macrophages at the site of infection leading to a partial activation of the immune cells." (PMID 18544042, 2008). "In a study based on a mice model, due to the effect of pro-inflammatory cytokines such as IL-1α′ and TNF-α′ in early infection, there was mild inflammation with low and stable concentrations of PGE2, which contributed to an efficient iNOS expression permitting temporal control of the infection." (PMID 19468469, 2008).
infection (continued). "LPS stimulated splenocytes released comparable amounts of cytokine from the two groups of animals prior to infection but four days following Salmonella translocation, LPS stimulated TNF-α, IL-6 and MCP-1 release was significantly less in the B. infantis-fed animals." (PMID 18670628, 2008). "Large cohort studies have shown an increase in the rate of infection in patients on anti-TNF therapy when compared to DMARDs alone, particularly within the first six months of treatment, but this has not been replicated in all randomised controlled studies and observational cohort studies." (PMID 19046446, 2008). "It is likely that chronicperiodontal infection may evoke an immune response that may result in the productionof slightly higher levels of TNF-α." (PMID 18320014, 2007). "In a recently published report we showed that the overall risk of severe infection was not increased following anti-TNFα therapy." (PMID 17763441, 2007). "Blockade of TNFα immediately after LCMV-infection prevents the development of T1D." (PMID 23675028, 2007). "Blocking of TNFα with a TNFR55-IgG1 fusion protein immediately after LCMV-infection abrogates T1D." (PMID 23675028, 2007). "The various activities of IL-6 and TNF-alpha suggest that thesefactors could play a major role in mediation of the inflammatoryand immune responses initiated by infection or injury." (PMID 17497030, 2007). "In 2 recently published studies from Germany and the UK, the infection rates observed in the anti-TNFα cohorts were very similar, but the 2 groups of investigators drew very different conclusions, the former estimating a doubling of risk and the latter no increased risk." (PMID 17763441, 2007). "In order to study the extent and kinetics of the inflammatory response, we sacrificed WT, TLR2 KO, and TLR4 KO mice at multiple time points after infection and measured the concentrations of the proinflammatory cytokines TNFα and IL6 and the anti-inflammatory cytokine IL10 in lung homogenates." (PMID 17676990, 2007). "This last scenario would also have resulted in an underestimation of the rate of serious infections in the anti-TNFα cohort in a “receiving treatment” analysis, and the analysis of the 90-day lag window might be a better reflection of the true rate." (PMID 17763441, 2007). "Thus, the main physiological effect of TNF-α is to promote the immunological and inflammatory response by recruiting neutrophils and monocytes to an infection site followed by their activation." (PMID 17505610, 2007). "If a patient in the anti-TNFα cohort developed an incident serious infection, the physician made an active treatment decision about whether therapy should be continued once the acute infection had resolved." (PMID 17763441, 2007). "Our recent data from a mouse model showed that treatment with anti-TNF Ab in the chronic phase rapidly resulted in fulminant TB, while treatment with an etanercept-like molecule (receptor fusion) allowed mice to maintain control of the infection." (PMID 17953477, 2007). "After 90 days of infection aminoguanidine (AG) or anti-TNFα antibodies were administrated." (PMID 18086300, 2007). "Our study suggests that a TNF-modulating agent could be developed that could balance the requirement for reduction of inflammation with the necessity to maintain resistance to infection and microbial diseases." (PMID 17953477, 2007). "TNF-α plays an important role in the host defense against infection." (PMID 17129374, 2006). "In our study, TNF-α was significantly elevated in the BALF shortly after infection with RSV." (PMID 16893457, 2006). "Monocytes/macrophages are the primary secretors of TNF-α during inflammation and infection." (PMID 16581537, 2006). "However, M. leprae induced TNFα mRNA expression upon infection of cells but at a lower level than as compared with BCG." (PMID 16978419, 2006).
infection (continued). "These are typical events of early acute BM and may correlate with an increase in the CSF levels of TNF-alpha at the very beginning of the inflammatory reaction, peaking at 12 h after infection, i.e. before the first assessment in this study (22 h)." (PMID 16749930, 2006). "LL-37 also reduced production of the pro-inflammatory cytokine TNF-α from macrophages stimulated with LPS and may be responsible for the migration of immune cells to areas of inflammation and infection." (PMID 16503962, 2006). "Hence, at 0.2 ng of p24 antigen of VSV-G pseudotyped HIV-1/fragment, the increase of replication by TNF-α is only observed at 120 h post-infection whatever the cytokine concentration." (PMID 16796744, 2006). "However, long-term control of infection appears to be dependent additionally on soluble TNF, as mem-TNF mice eventually succumb to chronic infection as shown by a recent contribution." (PMID 16285886, 2005). "Ex vivo restimulation 30 days after infection of splenic lymphocytes with mycobacterial antigens (SupBCG), but not with an irrelevant antigen, induced IFNγ secretion in cells from both TNF-KO and mem-TNF mice." (PMID 16285886, 2005). "We show that membrane TNF substitutes soluble TNF to recruit and activate macrophages and T cells, to generate granuloma and control acute infection, but is insufficient to control the chronic phase of infection." (PMID 16285886, 2005). "Within 4–5 weeks of infection TNF-KO mice displayed rapid weight loss (not shown), impeded locomotor activity and succumbed to infection rapidly." (PMID 16285886, 2005). "At 30 days post infection the lungs of mem-TNF mice displayed well-defined granulomatous lesions that were characterised by foamy epitheloid like macrophages with surrounding and interspersed and perivascular lymphocytic infiltration, similar to the granuloma structures formed in WT mice." (PMID 16285886, 2005). "However, infection with rAd.IκBα enhanced apoptosis induced by TNF-α approximately two-fold (range 1.9- to 2.5-fold) (compare bar 8 with bar 6)." (PMID 14520472, 2003). "In such patients, however, the infection with R. equi, a facultative intracellular pathogen which survives and replicates within macrophages, may be responsible for the impairment in the TNF-α release, possibly enhancing the HIV-induced macrophage dysftmction." (PMID 18475656, 1995). "TNF-α encodes Tumor Necrosis Factor alpha (TNF-α) which is a powerful pro-inflammatory cytokine, a chemical messenger from the immune system, produced mainly by macrophages, that regulates inflammation, cell death (apoptosis), fever, and the body’s response to infection and cancer." (PMID 41596367, 2026). "In chronically S. haematobium‐infected adults with low intensities of infection, stimulation of PBMCs ex vivo with adult worm antigen (AWA) resulted in higher secretion of TGFβ and IL‐10 by female‐derived cells, but lower secretion of Th1‐associated TNF and IFNγ." (PMID 41546136, 2026). "Likewise, therapeutic interventions including TNF-α blockade and glycemic control with metformin did not reverse infection-induced weight loss; moreover, TNF-α blockade failed to improve liver pathology." (PMID 42264147, 2026). "Moreover, ΔarrS infection resulted in an upregulation of TNF-α and IFN-γ in mice." (PMID 39980697, 2025). "Our observed anti-tumoural role of TNF-alpha during ZIKV oncolysis, its reported antiviral property, and our in silico prediction of its involvement in anti-tumoural immune responses highlight that oZIKV infection could likely be augmented by adjuvant therapy targeting TNF-alpha." (PMID 40240536, 2025). "Furthermore, we observed that pro-inflammatory mediators including IFN-α, IL-1β, IL-16, NF-κB, and TNF-α exhibited similar dynamic patterns, with their expression levels progressively increasing during early infection, peaking at 36 h, and subsequently declining with prolonged infection time." (PMID 41305370, 2025).
infection (continued). "Based on the sequencing results, we found that the NF-κB and TNF signaling pathways, cytokine and cytokine receptor interactions, IL-17 signaling pathway, and Toll-like receptor signaling pathway were upregulated after infection and downregulated after treatment." (PMID 40742124, 2025). "Nevertheless, infection of MH-S macrophages with the MtbΔctpA mutant resulted in the transcription or production of proinflammatory cytokines and microbicidal components essential for the control of Mtb during natural infection, such as IL-1β, IL-12, TNF-α, iNOS, and NADPH oxidase." (PMID 40002852, 2025). "PCI surgical trauma, ischemia–reperfusion injury, or postoperative infection can activate the immune system, leading to the massive release of inflammatory cells such as neutrophils and monocytes, and promoting the elevation of pro-inflammatory cytokines (such as IL-6 and TNF-α)." (PMID 40564453, 2025). "Moreover, the α-defensin-NTHi additive effect on MDMs is dependent on the viability of NTHi, suggesting that MDMs primed by α-defensins may respond faster and augmented TNFα secretion during NTHi infection." (PMID 40013145, 2025). "Phytochemical treatment of the cell line interfered with these pathways, resulting in a reduction in TNF-α production, which was more pronounced when the treatment was performed with subinhibitory concentrations (10 μg/mL) of AG, followed by αT, in case of Gram-positive strains infection." (PMID 40873569, 2025). "Similarly, levels of TNF-α and IL-1β were lower in 3d mice early in infection." (PMID 40248691, 2025). "In the middle stage of infection, the inflammatory response mainly depends on the TNF signaling pathway, the NOD like receptor signaling pathway, the IL‐17 signaling pathway, the AGE‐RAGE signaling pathway, and may also be related to the Toll like receptor signaling pathway in the later stage." (PMID 38992966, 2025). "Therefore, the observed increase in Eiger expression following blood feeding and infection may not only be a direct response to these physiological conditions, but also an indirect consequence of microbe-mediated modulation of TNF signaling." (PMID 40608824, 2025). "Thus, the baseline increased secretion of TNF could perhaps partially explain the resistance the Ubi_K48R cell line shows upon infection with the MNoV_S99." (PMID 40395509, 2025). "Therefore, ovophospholipid-induced enhancement in TNF-α production by macrophages may contribute to more efficient response to infections." (PMID 40509141, 2025). "Furthermore, the ratio of IFN-γ to TNF-α was important in the outcome of infection." (PMID 40558956, 2025). "The accumulation of necrotic foci within tumors is linked to elevated tumor necrosis factor (TNF) secretion and activation of necroptosis, a form of regulated necrotic cell death implicated in the pathogenesis of neurodegenerative disease, infection, and cancer." (PMID 41429922, 2025). "Performing ProcartaPlex ELISA assays, we assessed whether the soluble TNF factors of these pathways (TNF-alpha, TNFSF9 and TNFRSF9) were secreted following infection and observed significantly increased secretion of TNF-alpha and TNFRSF9 from both USP7 and USP13 cells at 48 hpi." (PMID 40240536, 2025). "When infection occurs, neutrophils are rapidly recruited from the peripheral circulation to the infection site under the action of various chemokines (such as IL‐8, IL‐1β, tumor necrosis factor [TNF], endotoxin, prostaglandins, and leukotrienes [LTs]) to exert their innate immunity." (PMID 40060194, 2025). "The infection by pathogens activates immune cells, such as macrophages and neutrophils, prompting them to release substantial quantities of pro-inflammatory mediators, including tumor necrosis factor-α (TNF-α) and lnterleukin-1β (IL-1β), which in turn initiates a systemic inflammatory response." (PMID 41357214, 2025).